ASF1B (anti-silencing function 1B histone chaperone)
Diseases named in the same sentence as ASF1B in open-access papers (continued):
Sharing a sentence is not in itself a finding about the gene and the disease.
lung carcinoma (11 papers, 2015 to 2025). "Since lung cancer is predisposed to invasion and metastasis, we used the Transwell assay to evaluate the effect of ASF1B on the migratory and invasive ability of lung cancer cells." (PMID 38164276, 2024). "Our study also found that the inhibitor of AKT significantly inhibited the malignant behavior of lung cancer cells, and this inhibitory effect was greatly reduced in ASF1B-overexpressed cells." (PMID 38164276, 2024). "ASF1B promoted the proliferation, migration, and invasion of lung cancer cells by regulating the phosphorylation of AKT in vitro." (PMID 38164276, 2024). "ASF1B-overexpressing and knockdown cell lines were constructed to explore its effects on the biological behavior of lung cancer cells." (PMID 38164276, 2024). "To further emphasize the impact of ASF1B on the biological behavior of lung cancer cells, we constructed ASF1B-knockdown cell lines by shRNA-mediated gene silencing in A549 cell lines." (PMID 38164276, 2024). "Furthermore, to further confirm this finding, we also assessed the effect of ASF1B overexpression on lung cancer cell proliferation by EdU marker staining." (PMID 38164276, 2024). "Compared to the cells in the control group, ASF1B-overexpressing cells had a significantly higher positive rate for EdU staining, indicating that ASF1B overexpression can promote the proliferation of lung cancer cells." (PMID 38164276, 2024). "In lung cancer, ASF1B was reported to regulate EMT and metastasis." (PMID 36114946, 2023). "ASF1B upregulation is previously suggested to be correlated with the EMT in lung cancer." (PMID 36114946, 2023). "We found that both RAD6A and RAD6B showed downregulated expressional levels in human lung cancers compared with normal lung tissues, while the expression of both ASF1A and ASF1B are upregulated." (PMID 26336826, 2015).
hepatocellular carcinoma (9 papers, 2021 to 2026). A malignant tumor that arises from hepatocytes. "In hepatocellular carcinoma 32, 33, ASF1B was also found to be associated with multiple immune-infiltrating cells and immune function signaling pathways, but it was different from our study." (PMID 38164276, 2024). "In this study, we found that the high expression of ASF1B in HBV-infected hepatocellular carcinoma patients was mostly associated with cell cycle-related pathways." (PMID 35280822, 2022). "In addition, GSEA showed that ASF1B is associated with cell cycle pathways in the progression of HBV-infected hepatocellular carcinoma." (PMID 35280822, 2022). "Interestingly, ASF1B was considered to be associated with immunotherapy efficacy in both hepatocellular carcinoma as well as LUAD, however, the correlation between ASF1B expression and the abundance of immune cell infiltration was clearly different in these two cancers." (PMID 38164276, 2024). "Particularly in hepatocellular carcinoma and male thyroid cancer, ASF1B was proposed as a potential target and immunological marker for tumor therapy." (PMID 36114946, 2023). "Our study showed that ASF1B is an independent prognostic factor in HBV-infected hepatocellular carcinoma and that its high expression leads to a poor prognosis in multiple survival types." (PMID 35280822, 2022). "The analysis of samples from the TCGA database revealed that ASF1B was highly expressed in hepatocellular carcinoma tissues, especially HBV-infected hepatocellular carcinoma samples." (PMID 35280822, 2022). "As verified by expression and prognosis, ASF1B was highly expressed in HBV-infected hepatocellular carcinoma and led to a poor prognosis." (PMID 35280822, 2022). "Bioinformatic analysis identified ASF1B as an independent prognostic factor in HBV-infected hepatocellular carcinoma, and its high expression led to a poor prognosis." (PMID 35280822, 2022). "Subsequent univariate and multifactorial Cox regression analyses were performed, and ASF1B was found to be an independent prognostic factor for HBV-infected hepatocellular carcinoma." (PMID 35280822, 2022). "We also compared the levels of ASF1B protein in normal liver cell line LO2 with four hepatocellular carcinoma cell lines such as Huh7, HepG2, MHCC97H and Hep3B." (PMID 35087760, 2021). "ASF1B possessed fortified expression, and ASF1B absence could accelerate apoptosis, together with cell cycle arrest in hepatocellular carcinoma." (PMID 36947060, 2023). "This suggests that ASF1B may promote the progression of HBV-infected hepatocellular carcinoma by affecting cell cycle-related signaling pathways." (PMID 35280822, 2022). "Silence of ASF1B inhibited hepatocellular carcinoma cell growth in vitro." (PMID 35087760, 2021). "ASF1B was rarely described as a key oncogene regulating hepatocellular carcinoma growth." (PMID 35087760, 2021). "Taken together, these results suggest that the oncogenic gene ASF1B could be a target for inhibiting hepatocellular carcinoma cell growth." (PMID 35087760, 2021). "Additionally, another study pointed out that the oncogene ASF1B may be the target of inhibiting the growth of hepatocellular carcinoma cells." (PMID 35875094, 2022). "However, the prognostic value and effect of ASF1B on tumor cells and the immune microenvironment in hepatocellular carcinoma (HCC) remain unclear." (PMID 35360875, 2022). "However, the expression and function of ASF1B in hepatocellular carcinoma remain to be determined." (PMID 35087760, 2021). "In this study, we analyzed the prognostic significance of ASF1B expression on OS, DFS, DSS, and PFS in HBV-infected hepatocellular carcinoma patients." (PMID 35280822, 2022). "We also verified the protein expression of ASF1B in four hepatoma cell lines (Huh7, HepG2, MHCC97H, Hep3B), and the abundance of ASF1B protein was increased in cancer cells compared with immortalized LO2 human hepatocytes." (PMID 35087760, 2021).
hepatocellular carcinoma (continued). "The results showed that ASF1B was highly expressed in HBV-infected compared to non-HBV-infected hepatocellular carcinoma tissues." (PMID 35280822, 2022). "We demonstrated the interaction between ASF1B and CDK9 in hepatocellular carcinoma cells." (PMID 35087760, 2021).
gastric cancer (8 papers, 2021 to 2026). A primary or metastatic malignant neoplasm involving the stomach. "Identified as an oncogene, ASF1B plays a significant role in tumor progression and holds considerable potential as a therapeutic target for gastric cancer." (PMID 40041497, 2025). "Overexpression of ASF1B in gastric cancer cells resulted in a reduced proportion of cells arrested in the G0/G1 phase, consistent with GSEA findings." (PMID 40041497, 2025). "ASF1B was first found to promote gastric cancer progression by downregulating H2AC20 to affect the activation of PI3K/AKT and ERK1/2 signaling pathways." (PMID 40041497, 2025). "Conversely, gastric cancer cells with ASF1B overexpression demonstrated enhanced proliferation compared to controls." (PMID 40041497, 2025). "We confirmed the promotional impact of ASF1B on gastric cancer growth through in vivo, in vitro, and organoid studies." (PMID 40041497, 2025). "Our research revealed that ASF1B expression was significantly elevated in GC, showing high expression across various gastric cancer subtypes." (PMID 40041497, 2025). "ASF1B overexpression in gastric cancer cells promotes cell cycle progression and inhibits apoptosis." (PMID 40041497, 2025). "Overall, these experiments confirm that ASF1B overexpression significantly promotes gastric cancer cell proliferation." (PMID 40041497, 2025). "Taken together, these data revealed that ASF1b expression promoted the proliferation, migration and invasion of gastric cancer cells in vitro." (PMID 35399734, 2022). "Additionally, flow cytometry indicated that ASF1B knockout promotes apoptosis in gastric cancer cells." (PMID 40041497, 2025). "In conclusion, we have substantiated the upregulation of ASF1B expression in gastric cancer tissues through comprehensive bioinformatics analyses and experimental validation, affirming its function in facilitating tumor growth in both in vivo and in vitro models, as well as organoid systems." (PMID 40041497, 2025). "Patient-derived gastric cancer organoids were generated, with ASF1B overexpressed." (PMID 40041497, 2025). "ASF1B knockdown reduced the expression of the proliferation marker Ki67 in gastric cancer tissues." (PMID 40041497, 2025). "H2AC20 was overexpressed in ASF1B-overexpressing gastric cancer cells." (PMID 40041497, 2025). "The role of ASF1B in gastric cancer was explored using both knockout and overexpression cell lines." (PMID 40041497, 2025). "Anti-silencing function 1b (ASF1b) was discovered as an oncogenic indicator for gastric cancer." (PMID 37693891, 2023). "However, detailed mechanisms of ASF1b tumorigenesis in gastric cancer remain elusive." (PMID 35399734, 2022). "We overexpressed H2AC20 in ASF1B-OE gastric cancer cells and discovered that H2AC20 can reverse the promoting effects of ASF1B on gastric cancer cell proliferation and invasion, as well as the influence of ASF1B on the cell cycle and apoptosis." (PMID 40041497, 2025). "For example, anti-silencing function 1B (ASF1B), a highly conserved histone chaperone protein, was found to interact with the transcription factor FOXM1 in gastric cancer cells, resulting in the increased enrichment of FOXM1 in PRDX3 promoter for PRDX3 transcription." (PMID 40227215, 2025).
clear cell renal cell carcinoma (7 papers, 2021 to 2023). "Recent studies indicated that ASF1B was overexpressed in clear cell renal cell carcinoma, and its upregulation boosted cancer cell growth by activating the AKT pathway." (PMID 34872448, 2021). "Similarly, ASF1B has been shown to be highly expressed in clear cell renal cell carcinoma (ccRCC), where its expression is dependent on the AKT/P70 S6K1 pathway and is correlated with tumor stage, tumor grade, and patient prognosis." (PMID 34472711, 2021). "In renal clear cell carcinoma, PKMYT1 was up-regulated and PKMYT1 was positively correlated with the anti-silencing effects of ASF1B gene." (PMID 36947060, 2023). "ASF1B motivated the AKT signalling to facilitate cell proliferation and migration in renal clear cell carcinoma." (PMID 36947060, 2023).
cell renal cell carcinoma (6 papers, 2020 to 2024). "In renal cell carcinoma, overexpression of ASF1B enhanced cell proliferation through up-regulating PCNA (proliferating cell nuclear antigen)." (PMID 34906203, 2021).
lung adenocarcinoma (6 papers, 2021 to 2024). A carcinoma that arises from the lung and is characterized by the presence of malignant glandular epithelial cells. "In recent years, the role of ASF1B in the progression of other cancers has been explored; high ASF1B expression has pointed to a poor prognosis for lung adenocarcinoma and has been associated with advanced tumor stage and tumor progression." (PMID 35280822, 2022). "A previous study has illuminated that enhancive ASF1B expression has a relation with the poor prognosis of lung adenocarcinoma." (PMID 36947060, 2023). "Anti-silencing function 1B histone chaperone (ASF1B) is known to be an important modulator of oncogenic processes, yet its role in lung adenocarcinoma (LUAD) remains to be defined." (PMID 34568067, 2021). "However, the significance of ASF1B in lung adenocarcinoma (LUAD) is largely overlooked." (PMID 38164276, 2024).
glioma (5 papers, 2021 to 2023). A benign or malignant brain and spinal cord tumor that arises from glial cells (astrocytes, oligodendrocytes, ependymal cells). "ASF1B demonstrated a high diagnostic value in glioma patients, according to a Receiver Operating Characteristic (ROC) analysis." (PMID 35875094, 2022). "Meanwhile, the AUC of ASF1B in the diagnostic assessment of glioma was 0.985, indicating that ASF1B is a possible glioma biomarker." (PMID 35875094, 2022). "All of these findings revealed that increased ASF1B expression was linked to poor prognosis in glioma patients." (PMID 35875094, 2022). "The survival analysis found that increased ASF1B expression was linked with a poor prognosis in glioma patients." (PMID 35875094, 2022). "Association of ASF1B expression and clinicopathological parameters in patients with gliomas." (PMID 35875094, 2022). "In glioma patients, upregulation of ASF1B was statistically linked to a poor prognosis." (PMID 35875094, 2022). "We investigated ASF1B expression levels in gliomas and normal tissues and discovered that glioma tissues had considerably higher levels of ASF1B expression (p <0.001)." (PMID 35875094, 2022). "ASF1B mRNA expression provides a high predictive value for the prognosis of glioma patients at 1, 3, and 5 years, according to a time-dependent ROC analysis of ASF1B expression in glioma patients." (PMID 35875094, 2022). "To begin, we used transcriptome and clinical data from the TCGA and CGGA databases to investigate the predictive ability of ASF1B in gliomas, as well as probable mechanisms." (PMID 35875094, 2022). "The link between ASF1B expression levels and immune cell populations was investigated to assess the amount of immune infiltration in gliomas." (PMID 35875094, 2022). "According to the median mRNA expression levels of ASF1B, glioma patients were split into low and high expression groups." (PMID 35875094, 2022). "ROC analysis was used to determine the efficiency of ASF1B mRNA expression levels in distinguishing gliomas from normal tissues, with an estimated AUC of 0.985 (95% CI: 0.980–0.989)." (PMID 35875094, 2022). "We analyzed the DEGs between low and high expression of ASF1B groups to further explore the potential mechanisms of ASF1B that participate in glioma progression." (PMID 35875094, 2022). "In our investigation, we discovered that ASF1B was substantially expressed in glioma tissues and that it indicated a poor outcome for individuals with gliomas." (PMID 35875094, 2022). "In summary, the findings indicate that ASF1B can serve as a novel prognostic biomarker for glioma patients." (PMID 35875094, 2022). "In summary, ASF1B expression levels were positively correlated with a poorer prognosis in glioma patients." (PMID 35875094, 2022). "The relationship between ASF1B expression and several clinical features of glioma patients was investigated." (PMID 35875094, 2022). "In this study, we first used the Cancer Genome Atlas (TCGA) database to confirm the prognostic value of ASF1B expression in glioma patients, and then validated the value using the Chinese Glioma Genome Atlas (CGGA) database." (PMID 35875094, 2022). "ASF1B exhibited different expression profiles in different tumors and was significantly upregulated in glioblastoma and low-grade glioma." (PMID 35875094, 2022). "To further identify the potential role of ASF1B in gliomas, we analyzed DEGs between low and high expression groups of ASF1B and performed functional enrichment analysis." (PMID 35875094, 2022). "ASF1B expression was shown to be considerably higher in glioma tissues, and it was linked to high-grade gliomas, advanced age, wild-type IDH, and 1p19q non-codeletion, suggesting that ASF1B plays a role in the disease process of gliomas." (PMID 35875094, 2022). "This study confirmed the importance of ASF1B in gliomas from multilevel analysis and demonstrated that ASF1B might be a novel prognosis biomarker and therapeutic target for gliomas." (PMID 35875094, 2022).
glioma (continued). "We used enrichment analysis and GSEA analysis to learn more about the biological functions and pathways that ASF1B may participate in the development of gliomas." (PMID 35875094, 2022). "Prognostic analysis of ASF1B expression in a subset of patients with gliomas." (PMID 35875094, 2022). "A high level of ASF1B mRNA expression was correlated with a poor prognosis in glioma patients in this study, implying that it could be a reliable prognostic biomarker for glioma patients." (PMID 35875094, 2022). "In glioma tissues, ASF1B expression was considerably higher than in normal tissues." (PMID 35875094, 2022). "However, the potential function of ASF1B in gliomas remains ambiguous." (PMID 35875094, 2022). "Therefore, we speculate that ASF1B may also participate in the functional regulation of gliomas." (PMID 35875094, 2022). "Thus, ASF1B may participate in glioma tumorigenesis by regulating cell proliferation." (PMID 35875094, 2022). "Regarding the expression of ASF1B protein in gliomas, we found that the immunohistochemical analysis of ASF1B was positive in gliomas but negative in normal tissues." (PMID 35875094, 2022). "But the values of ASF1B in gliomas have not been elucidated and further confirmation is needed." (PMID 35875094, 2022).
multiple myeloma (5 papers, 2021 to 2023). "MiR-214 inhibited the proliferative ability and promoted the apoptotic rate of myeloma cells by down-regulating ASF1B." (PMID 36947060, 2023). "The expression of ASF1B can also promote multiple myeloma progression." (PMID 35280822, 2022). "In addition, previous reports confirmed that miR-214-3p could inhibit the progression of multiple myeloma by targeting ASF1B, as well as being regulated by lncRNA SNHG3 to affect the development of papillary thyroid carcinoma." (PMID 34336642, 2021). "In multiple myeloma, LINC00665 upregulates PSMD10 and ASF1B by sponging miR-214-3p, thereby promoting proliferation and inhibition of apoptosis of multiple myeloma cells." (PMID 35563845, 2022).
thyroid cancer (5 papers, 2021 to 2025). "Our results indicate that ASF1B can be considered a prognostic marker, therapeutic target, and predictor of immunotherapy response in male thyroid cancer patients." (PMID 35174076, 2022).
liver cancer (4 papers, 2021 to 2022). An epithelial or non-epithelial malignant neoplasm that arises from the liver. "Kaplan-Meier survival curve showed that elevated ASF1B expression was associated with poor survival in patients with liver cancer." (PMID 35087760, 2021). "In HBV-positive liver cancer tissues, ASF1B was mainly enriched in signaling pathways related to cell cycle progression." (PMID 35280822, 2022). "In conclusion, the present study is the first to analyze ASF1B based on HBV-infected liver cancer tissues." (PMID 35280822, 2022). "Overall, our results indicated that ASF1B expression was significantly higher in liver cancer (LIHC) relative to normal tissues." (PMID 35087760, 2021). "In this research, we used bioinformatics and multiple databases to comprehensively analyze the expression of ASF1B in pan-cancer, and found that ASF1B was abnormally expressed in most cancers, including liver cancer, which is consistent with current literature reports." (PMID 35087760, 2021). "Next, we evaluated the relationship between ASF1B expression and HCC cohort survival outcomes based on the Liver Cancer RNA-seq database of Kaplan-Meier Plotter and plotted the Kaplan-Meier survival curve." (PMID 35087760, 2021).